ENSG00000259316 (novel protein)
Gene: Protein-coding gene on chromosome 15 (64,181,180 to 64,381,440, reverse strand). Ensembl gene ENSG00000259316.
Genetic constraint (gnomAD): Missense variants: 100 observed, 120.67 expected, observed/expected ratio (o/e) 0.83, 90% interval 0.7 to 0.98. Synonymous variants: 30 observed, 43.29 expected, observed/expected ratio (o/e) 0.69, 90% interval 0.52 to 0.94.